CD69 (CD69 molecule)
Diseases named in the same sentence as CD69 in open-access papers (continued):
Sharing a sentence is not in itself a finding about the gene and the disease.
infection (continued). "To determine whether the T cells were activated following infection, we stained the T lymphocytes for the expression of the activation markers CD69, CD44/CD62L, CD40L." (PMID 23555767, 2013). "Therefore, in order to exclude the possibility that we were only detecting infection of the cells showing early signs of activation, we depleted CD69+ cells from the SNARFhiEGFP− T cells at day 5 post-infection prior to co-culture with PHA and feeder PBMC." (PMID 24339779, 2013). "To check for a possible role of CD69 expressed by either DC or T cells on T cell priming in a physiological model of infection, in which more factors and possible indirect effects can also play a role, we used various experimental settings of the Vaccinia virus (VACV) infection model." (PMID 23119065, 2012). "Interestingly, the proportion of CD11ahi cells in the BAL remained unchanged for the first 48 hours of secondary infection, even though CD69 increased among these cells." (PMID 21647373, 2011). "Furthermore, phenotyping SIV infected cells in situ demonstrated marked and selective infection of CD69+ T cells in tissues, which is also consistent with direct infection of CD4+ T cells." (PMID 22096538, 2011). "CD69 expression diverged at day 28 post-infection, when C57Bl/6 T cells had CD69 levels comparable to controls and Balb/c T cells had 3.2±0.8 fold increased CD69 expression compared to controls (p = 0.0002) and compared to the previous time point (1.9±2.6 p = 0.004)." (PMID 20625554, 2010). "CD69 expression on total T cells was similar early during infection for both models." (PMID 20625554, 2010). "In contrast, the percentage of NP147-155 specific activated CD8+ T-cells were not statistically different between aged and adult animals; nevertheless, adult animal had a higher percentage of CD8+/CD69+ NP-pentamer+ T-cells between days 9 and 11 post-infection." (PMID 19922665, 2009). "However, on days 4 and 6 p.i. with vΔN1L there was a significantly smaller proportion of lymphocytes (both NK and T cells) that was CD69+ compared with the proportion following infection with WT and Rev viruses." (PMID 18931086, 2008). "An interesting parallel to the results reported here with the VACV N1 protein is the reduction in CD69 activation on B cells, which correlated with a decrease in splenomegaly, following infection with murine herpes virus 68 engineered to lack a viral Bcl-2 protein (vBcl-2)." (PMID 18931086, 2008). "The higher levels of early (CD69) as well as late (HLA-DR) T-cell activation markers in mono-infected individuals are most likely induced by continuous antigenic challenge and ongoing infection from residence in an area of high hookworm transmission." (PMID 17576364, 2007). "Finally, an in vivo mouse model of E. coli pneumonia demonstrated that CXCR4+ and CD69+ T cells are rapidly recruited from the blood to the lung during the peak of infection further supporting the role of the ALARM module in mediating immune cell recruitment to sites of inflammation." (PMID 41531734, 2026). "Our finding that CD11c+ dendritic cells isolated from the Peyer's patches of rotavirus-infected mice had increased upregulation of CD69 supports previous findings that, following rotavirus exposure, Peyer's patch dendritic cells appear to be activated and increased in number following infection." (PMID 40304491, 2025). "To determine if infection activated other cell types in the Peyer's patch concurrently with the B cells, we prepared leukocyte single cell suspensions from the Peyer's patches of infected mice and assessed them for the activation marker CD69 expression by flow cytometry." (PMID 40304491, 2025). "However, CD69 is also an activation marker upregulated by lymphocytes during infection." (PMID 36159876, 2022). "This suggests that CD69 may help lymphocytes migrate to the site of infection." (PMID 32849474, 2020).
infection (continued). "To investigate whether NK cells might be primed for homing to peripheral tissues during acute DENV infection, we determined the chemokine receptor profile of Ki67+/CD69+ and Ki67−/CD69− CD56bright and CD56dim NK cells, respectively, during the acute phase of infection." (PMID 31467285, 2019). "Furthermore, on day 40 post-infection, more CD69+ memory P14 CD8+ T cells were present in the skin infected with VacV-GP33 compared to the skin infected with VacV-OVA, demonstrating that local antigen recognition in the skin increased the retention of antigen-specific secondary TRM CD8+ T cells." (PMID 30875408, 2019). "It is also notable that a larger fraction of M-specific CD69+ TRM cells elicited by vaccination with MCMV coexpressed CD103 compared with either M2-specific CD69+ TRM cells elicited by vaccination with MCMV or TRM cells of either specificity elicited by infection with RSV." (PMID 30154789, 2018). "Furthermore, TRM found within the interstitium, unlike vascular-associated TRM, were able to up-regulate CD69 expression, potentially indicating an enhanced ability to respond during early infection." (PMID 30038624, 2018). "Similarly, in an experimental human challenge study, an abundance of CD69+CD103+ RSV-specific CD8+ T cells in lung before infection correlated with reduced symptoms and viral loads, implying that CD8+ TRM cells in the human lung play an important role in protection against RSV disease." (PMID 29121080, 2017). "For instance, as the CPS confers a survival advantage to GBS, persistence of GBS within antigen-presenting cells may affect their activation and thus the ensuing T cell immune response, including altered IFN-γ and CD69 expression balance early during infection." (PMID 26989699, 2016). "However, untreated CD4+ T cells from splenic tissue—which expressed CD69 at levels comparable to those of CD4+ T cells isolated from tonsillar tissue—did show an increase in productive infection (1.8%) as compared to untreated CD4+ T cells from peripheral blood." (PMID 26067822, 2015). "As such, the association between lack of detectable viral replication on day 9 post-inoculation and reduced baseline frequencies of CD4+ CD69+ T cells supports the hypothesis that T cell immune quiescence can limit infection by reducing the pool of activated HIV target cells." (PMID 23029309, 2012). "A multiparameter flow cytometry panel, including six common activation markers: CD40L, CD137, CD69, OX40, CD25, and PD-L1, was used for detecting antigen-specific T cells following infection (SARS-CoV-2 and CMV) or vaccination (mRNA-1273 SARS-CoV-2)." (PMID 41811887, 2026). "For instance, intracerebral delivery of vesicular stomatitis virus (VSV) antigens was required to sustain CD69 and CD103 expression on brain CD8+ T cells, with CD103+ clusters persisting up to 30 days post-infection, even after viral clearance." (PMID 41479900, 2025). "We found that while blood eosinophil counts quickly and dramatically dropped after the infection with SARS-CoV-2, their phenotype changed into CD69/CD125/CD63high and CD44/CCR3low." (PMID 40710346, 2025). "Two weeks after the XBB.1.5 infection, we detected a population of S-specific CD8 T cells in the BAL that co-expressed the canonical TRM markers CD69 and CD103." (PMID 40562777, 2025). "Consistent with pre-infection observations, sustained and expanded ESAT6:I-A(b)+CD69+ T cells in the lung parenchyma (CD45.2−) were confirmed upon CDG addition at 10 weeks post-Mtb K infection." (PMID 40414893, 2025). "While CD69 promotes the accumulation and retention of CD8+ T cells in the lung during the early phase of infection, the maintenance of pathogen-specific memory CTLs in the respiratory tract is more likely due to the adhesive function of CD49a and CD10311,40." (PMID 40240341, 2025). "Our results showed significantly reduced CD69 levels in monocyte–macrophages and neutrophils of TLR7−/− lungs compared to control mice at day 2 post-infection." (PMID 40162785, 2025).
infection (continued). "TRM cells, characterized by CD69 and CD103 expression, reside at pathogen entry sites and provide rapid first-line defense against infections." (PMID 41459157, 2025). "While CD103+ cells also showed increased CD69 and ICOS expression post-infection, the changes were less pronounced than in CD103− cells." (PMID 41459157, 2025). "We first monitored by flow cytometry lymphocyte proliferation using carboxyfluorescein succinimidyl ester (CFSE) dilution assay, as well as lymphocyte activation based on the expression of surface markers CD69, CD25, HLA-DR, and CD38 on day 6 post-infection." (PMID 40162896, 2025). "In a mouse model of encephalomyocarditis virus (TMEV) infection, CD69+ CD103‐ TRM were observed to proliferate within 24 h, while antigen‐specific CD103+ CD69+ TRM appeared on Day 15 post‐infection and lingered for up to 60 days or longer." (PMID 41388658, 2025). "Before booster infection, the expressions of the TRM markers CD49a and CD69 were similar in 6 m primed and 9 m primed mice, but CD103 expression was reduced in 6 m primed mice." (PMID 38675801, 2024). "Activation markers CD69 and CD25 and type I IFN–inducible marker CD317 were promiscuously expressed, undergoing upregulation in virtually all cell types following infection." (PMID 38814732, 2024). "At day 7 post-infection, when virus-specific T cells are first detected, 40–50% of SARS-CoV-2-specific CD4 and CD8 T cells in the BAL express CD69, and <10% of CD8 T cells co-expressed CD69 and CD103." (PMID 38950078, 2024). "We found that the CD103+CD49a+ population is maintained as a long-term CD69+CD38+CXCR6+ Trm subset in the liver, which showed rapid expansion and cytokine production after secondary infection." (PMID 39392861, 2024). "There was a 3-fold defect in the frequency of CD69/CD103 double-positive cells among S- and N-specific CD4 T cells in the BAL at 4–5 weeks post-infection in the anti-IL-10 treatment group relative to controls." (PMID 38950078, 2024). "The significantly downregulated genes (NEAT1, TPM3, ZNHBA, CKLF, and OSBPL8) and the upregulated genes (ITMZC, IFNG, CD69, DNAJB9, and LYST) in NCAM1+FCGR3A+dNK cells after infection were also analyzed." (PMID 38730500, 2024). "After controlling for changes in surface marker expression frequency, the infection frequency of CCR5, α4β7, CCR5 + α4β7, CXCR4, and CD69 expressing CD4+ T cells remained greater in the EM of women following menopause." (PMID 39872519, 2024). "In this study, using two methods, CD69 expression and ex vivo cytokine staining, we showed that early activation of lymphocytes indeed had taken place after ASFV CADC_HN09 infection." (PMID 38419627, 2024). "Ifne-/- mice have fewer CD69+IFNγ+ double-positive and CD69+IFNγ- single-positive NK cells in the upper FRT during infection compared to WT controls." (PMID 38263527, 2024). "We determined which part of the ASN- and SSL-specific T-cell population was expressing CD49a, CD69, and/or CD103 and compared this between tissues (blood vs lung) and infection histories (6 m primed vs 9 m primed mice)." (PMID 38675801, 2024). "At 60 days post‐infection, these mice also showed increased frequencies of CD4+ T cells with activation (CD25+, CD69+ CD25+) and effector memory (KLRG1+) markers in the lungs." (PMID 39039808, 2024). "Further examination of CD69 and ex vivo expression of IFN-γ on immune cells showed that T cells were transiently activated and expressed IFN-γ as early as 5 days post-infection." (PMID 38419627, 2024). "At 60 days post‐infection, the spleen of OM‐TB‐TKO mice contained significantly lower frequencies of CD3+ CD4+ T cells, CD69+ CD4+ T cells, CD25+ CD69+ T cells, PD1+ CD27− T cells, and TIM3+ CD4+ T cells, when compared against O‐TB‐TKO or Y‐TB‐TKO mice." (PMID 39039808, 2024). "NK cells from MCMV-infected mice were highly activated, as indicated by their upregulation of the activation markers CD69 and CD43 on D3 post-infection." (PMID 37553427, 2023).
infection (continued). "Analysis of brain leukocytes in Lm 10403s-infected mice showed significant brain influxes of CD4+ and CD8+ T-lymphocytes, including sub-populations expressing the CD69 activation marker and TRM markers, as well as granulocytes, 1 mo after infection." (PMID 37143648, 2023). "Following on previous reports that demonstrate a preferential infection of CD69 expressing T lymphocytes we FACS sorted MAIT cells by CD69 expression into two populations: CD69- and CD69+ MAIT cells." (PMID 37006246, 2023). "We proceeded to characterize CD8 T cells present in RPE/c and neural retinas on day 8 after infection using markers typically responsible for endothelial adhesion (LFA-1), retention in tissues (CD69) and migration/positioning (CXCR6, CXCR3)." (PMID 37662932, 2023). "Classically defined CD8+ CD103+ CD69+ TRM cells in the lung and BAL were analyzed and found to be a major component of lung and BAL at 4 days after re-infection." (PMID 35108347, 2022). "Next, we evaluated both CD4+CD69+ as well as CD4+CD69+CD103+ TRM cell populations in the injected and distal flanks at both 6 and 15 weeks post-infection/immunization." (PMID 35419001, 2022). "During the first year of infection, the frequency of activated CD38+ or CD69+ iNKT cells strongly correlated with alanine transaminase levels with particularly pronounced correlations in spontaneously resolving patients." (PMID 34905514, 2022). "The most striking finding regarding the iNKT cell phenotype in different infection outcomes was the downregulation of CD38 and CD69 in the context of HCV resolution." (PMID 34905514, 2022). "Neomycin ‘pull’ increased accumulation of CD69+CD103+ local Trm and enhanced protection from subsequent infections to a similar extent as CXCL10." (PMID 35985020, 2022). "Tet3-deficient T cells were also impaired in their ability to populate the SG and LP at day 21 and showed an early defect in differentiation with reduced CD69 and CD103 expression on day 7 of infection compared to control IEL and LP T cells." (PMID 36156073, 2022). "CD103+ CD69+ CD8+ TRM cells produced IFN-γ and GzmB and these cells increased by day 4 post re-infection in the lung and airways." (PMID 35108347, 2022). "Of note, at SVR12, the HIV-HCV co-infected subjects displayed significantly higher CD69 + γδ + (p = 0.02), as well as CD38 + γδ + T-cells (p = 0.003) as compared to individuals with HCV mono-infection." (PMID 35893661, 2022). "Deficiency of TNFR1/2 resulted in greatly decreased numbers of CD69+ activated NK cells as early as D3, suggesting a key role of TNF signaling in regulating NK cell activation early during infection." (PMID 35479068, 2022). "It showed upregulation of multiple inflammatory transcripts, including Toll-like receptor 1/2 (TLR1/2), CD69, and CARD14, upon 5-ASKH infection." (PMID 36190414, 2022). "Of note, the same dynamic was observed in CD69 expressing CD4+ T cells, with a remarkable increase by day 4 post re-infection both in lung and airways." (PMID 35108347, 2022). "The magnitude of CD69 expression in the spleens and lymph nodes was higher than that in the blood on all the subsets we examined after ASFV HLJ/18 infection." (PMID 35746813, 2022). "FTY720 treatment during re-infection, revealed that both CD69+ and CD103+ CD69+ CD8+ TRM cells are expanded from pre-existing lung TRM cells with minor contribution from circulatory T cells." (PMID 35108347, 2022). "Both infection and vaccination similarly led to increased IV-CD45−tetramer+CD4+CD69+CD103− TRM cells." (PMID 36302057, 2022). "At week 4 post infection, activated CD4+CD69+ T cell numbers increased in both groups and the numbers were now equivalent at this timepoint." (PMID 35173157, 2022). "Altogether these results characterize the CD8+ T cell response during RSV secondary infection and show that functional RSV-specific CD69+ CD103+ CD8+ TRM cells in the lung and airways go through an expansion between days 3–4 post re-infection." (PMID 35108347, 2022).
infection (continued). "After the onset of infection, DENV-specific T cells expressed early activation marker CD69, and later displayed other activation markers such as CD38, CD71 and HLA-DR." (PMID 36423184, 2022). "Consistent with results on CD103 and CD69 expression, lung resident (i.v.-) RSV-specific CD49a+ and CXCR6+ CD8+ T cells peaked at day 4 post re-infection." (PMID 35108347, 2022). "(A) Representative histograms (top) and quantification (bottom) of CD69 MFI on NK cells and frequency of KLRG1+ and IFNγ+ NK cells at day 1.5 post-infection (pi) of 1αKO or FL control mice." (PMID 34396954, 2021). "The activation marker CD69 and proliferation marker Ki67, which are increased especially on CD8 T-cells after pH1N1 infection, were similarly transiently increased on CD8 T-cells after H5N1 infection in both combined-route as well as aerosol-exposed animals." (PMID 33671829, 2021). "Mice that were vaccinated with either the streptococcal vaccine Strep‐vax or Multi‐vax had significantly elevated levels of CD4+ T cells, CD69+ activated CD4+ T cells and CD8+ T cells following super‐infection compared to unvaccinated mice." (PMID 34527244, 2021). "Using confocal microscopy, we found that CD69+CD103+CD4+ and CD69+CD103+CD8+ T cells localized to the epithelial layer surrounding large airways during infection." (PMID 34564636, 2021). "Neutralization of IL-2 increased the numbers of recently activated CD4+CD69+ T cells and memory CD4 and CD8 T cells after three weeks of infection and the numbers of splenic T cells producing IFN-γ, TNF-α and IL-10." (PMID 34869064, 2021). "The CD69+CD103+ CD4+ and CD8+ T cells were maintained in the tissue during FTY720 treatment and proliferated during the course of infection." (PMID 34564636, 2021). "The percentages of CD69, ICOS, or CD80-expressing B cells increased in infected mice during the course of infection (p < 0.01)." (PMID 33588839, 2021). "In general, CD69 expression on CD4, CD8 and γδ T-cell populations was higher at the later post-infection timepoints and expression levels agreed with the detection of cytokine production in the corresponding T-cell subsets." (PMID 33627662, 2021). "CD8 CD69+CD103- T cells were also elevated early after infection, while CD8 TRM cells expressing both CD69 and CD103 were elevated in the late phase of infection." (PMID 34587172, 2021). "Within the CD69+ CD103+ compartment, 1M mLN cells showed a steady decline in frequency and total numbers from days 30 to 250 post-infection, while 4M CD8+ T cells were largely maintained in frequency and total numbers over the same time frame." (PMID 34143731, 2021). "Latent and productively infected tonsillar CD4+ T cells displayed similar activation profiles as measured by expression of CD69, CD25, and HLADR, however latent cells showed higher CXCR5 expression 3 days post-infection." (PMID 34531866, 2021). "In the liver, compared to mock-infected mice, the percentage of CD69+ CD4+ T-cells was significantly increased on days 4 and 8 PI indicating that CD4+ T-cells were rapidly activated following CCHFV infection." (PMID 33572859, 2021). "Activated CD8+ T cells exhibited increased expression of activation markers CD69 and TNFAIP3 with both infection and vaccination." (PMID 34935643, 2021). "These CD69+ CD4+ T cells up-regulated CD44 and CD103 expression over time after infection, indicating that BALB/c mice were able to induce TRM cells in the nasal tissue after Bp infection." (PMID 33420041, 2021). "By day 35, 4 weeks after infection, all remaining CD4+ cells were CD69+ TRM cells in these resting lungs, and they localized exclusively around the conducting airways." (PMID 34611166, 2021). "The proportion of CD69+ B cells and CD8 T cells was lower on day 4 post-infection in the 3D compared to the 2D model." (PMID 34603299, 2021). "Nevertheless, from day 30 after infection onward, pMT-10 mice displayed an increase in the frequency and number of CD4+ T cells expressing CD69 and Ki-67." (PMID 34554927, 2021).